RNU6-181P (RNA, U6 small nuclear 181, pseudogene)
Gene: Small nuclear RNA gene on chromosome 15 (100,560,686 to 100,560,792, reverse strand). Ensembl gene ENSG00000200095.
Homologues: Orthologues: chimpanzee U6 (100% identical), macaque U6 (98% identical), guinea pig U6 (83% identical), dog U6 (81% identical). Paralogues in human: RNU6-940P (91% identical), RNU6-1145P (90% identical), RNU6-1316P (89% identical), RNU6-16P (89% identical), RNU6-211P (89% identical), RNU6-29P (89% identical), RNU6-393P (89% identical), RNU6-434P (89% identical), RNU6-1075P (88% identical), RNU6-1152P (88% identical), RNU6-15P (88% identical), RNU6-188P (88% identical), and 1287 more.